DKK1 (dickkopf Wnt signaling pathway inhibitor 1)
Diseases named in the same sentence as DKK1 in open-access papers (continued):
Sharing a sentence is not in itself a finding about the gene and the disease.
cancer (continued). "The mechanism of action of anti-DKK1 via Wnt-dependent or Wnt-independent pathways reinforces the potential of this target for anti-angiogenic cancer therapy." (PMID 40394415, 2025). "In summary, the available preclinical and clinical data to date support the inhibition of DKK1 by our lead antibody panel as a therapeutic strategy for the treatment of cancer and bone metabolic diseases." (PMID 40394415, 2025). "Overexpression of PTHR1 or knockdown of the natural inhibitor of Wnt, DKK1, reversed the inhibitory effects of convallatoxin on cancer proliferation, migration, and invasion and enhanced osteogenic differentiation." (PMID 40427472, 2025). "Together, these data demonstrate that DKK1 is a driver of immune evasion in several cancers and represents an attractive target for immunotherapeutic discovery." (PMID 40394415, 2025). "Recently, dysregulated DKK1 expression was identified as a possible biological marker of cancer progression and a prognostic factor for a variety of malignancies." (PMID 38376441, 2024). "Initial research on the use of Dkk1 and other Wnt-inhibitors as a drug approach raises hopes for a broader range of therapeutic interventions in the setting of treating different cancers, including BC." (PMID 38254908, 2024). "TET1 potently inhibited canonical Wnt/β‐catenin signalling by demethylating and upregulating two upstream antagonists of this pathway, SFRP2 and DKK1, which was associated with inhibition of EMT and cancer cell metastasis." (PMID 37994489, 2024). "Co‐staining of DKK1 and S100 in the mouse xenograft tumors showed that the cancer cells invaded the nerve in DKK1‐overexpressing group." (PMID 38525111, 2024). "The analysis revealed significantly higher serum DKK1 levels in the advanced cancer patient group (1863.5 pg/mL; 62.5–4902 pg/mL; n = 32) than in the control group (504.8 pg/mL; 62.5–1260 pg/mL; n = 17); the AUC was 0.78." (PMID 38334454, 2024). "DKK1 was found to be mainly expressed in the cancer epithelial cells in the HER2+ subtype, and to a less extent in TNBC, while barely detectable in the normal epithelial cells." (PMID 38659818, 2024). "In the present study, elevated serum DKK1 levels were observed in patients with advanced cancer compared to those with endoscopically confirmed clean colon." (PMID 38334454, 2024). "Patients with quintuple positive cancers (HPV + CD147 + CD15 + p63 + DKK1) displayed a significantly reduced OS and MFS compared to clinical parameters (N, I, L, V)." (PMID 39333233, 2024). "RNA sequencing in cells treated with T6I-29 reveals a neomorphic downregulation of DKK1, a secreted glycoprotein known to play oncogenic roles in other cancers." (PMID 38978585, 2024). "The link between DKK1 expression and the infiltrating levels of immune cells in distinct cancer subtypes was examined using the TIMER database." (PMID 38376441, 2024). "According to newly discovered experimental data, the accumulation of MDSCs by DKK1 has been shown to contribute to T cell differentiation and the induction of cancer immune surveillance evasion." (PMID 38376441, 2024). "Dickkopf-1 (DKK1), a soluble antagonist of the Wnt/β-catenin signalling pathway, is elevated in the serum of patients with various cancers and animal models of chronic inflammatory diseases." (PMID 39236081, 2024). "DKK1-positive carcinomas showed significantly more DKK1-positive cells in the surrounding stroma than DKK1-negative carcinomas (p = 0.0002; Fisher’s exact test)." (PMID 39630300, 2024). "Here, we showed that DKK-1 had a similar role in the cancer progression of the osteoblastic canine Probasco cell line." (PMID 38067123, 2023). "DKK1 induces the expression of proteins related to cancer stem-like cells, promoting cell proliferation, migration, invasion, and VM in NSCLC." (PMID 37906341, 2023). "In AML, DKK1 is released by cancer cells to alter the stromal microenvironment for propagating the disease while hindering normal hematopoietic stem cell (HSC) activity." (PMID 36661526, 2023).
cancer (continued). "High expression of Wnt antagonists (i.e., sclerostin and DKK-1) has been detected in cancer patients with bone involvement and mouse models of cancer in bone, suggesting osteocyte production of these factors is affected by cancer cells in bone." (PMID 37174109, 2023). "As a member of a typical carcinogenic signaling pathway, DKK1 plays an important anticancer role in human cancers." (PMID 36447119, 2023). "The DKK-1 metastases induced cortical bone resorption, which enabled cancer cells to penetrate the cortex and grow outside the bone, leading to new periosteal bone formation." (PMID 38067123, 2023). "Cytoskeleton-associated protein 4 (CKAP4) binds to the DKK-1 and p85α subunit of PI3K to activate PI3K/AKT signal pathway to stimulate cancer cell proliferation." (PMID 36805679, 2023). "Overexpression of DKK1 is closely related to cancer development and poor survival in various cancers, including ESCA." (PMID 35780460, 2023). "Based on the findings of studies on DKK1 in cellular and animal models, several clinical trials have been initiated to evaluate the safety and efficacy of anti-DKK-1 neutralizing antibodies in cancer." (PMID 37907850, 2023). "We have shown that over-expression of DKK-1 in the canine osteoblastic PCa cell line Probasco stimulated cancer growth and attenuated the osteoblastic phenotype of bone metastases." (PMID 38067123, 2023). "The Dickkopf1 (DKK1) protein is involved in the inhibition of the Wnt signaling pathway that has a role in cancer development and progression." (PMID 36409488, 2023). "With the development of neutralizing antibodies against DKK-1, a new opportunity arose to repair damaged bone in lytic cancers." (PMID 37174109, 2023). "Apart from that, the moderating, amplifying, and side effects of Dkk1 treatment on cancer effect were comparable in SNU398 cells (48, 39, and 25 lipids represented in green, red, and orange bars, respectively)." (PMID 37699867, 2023). "This study aimed to explore the molecular role of DKK-1 in PCa progression and cancer–bone interactions using the canine osteoblastic Probasco PCa cell line." (PMID 38067123, 2023). "Quiescent cancer cells in distant organs that have tumor-initiating capacity express DKK-1, which inhibits Wnt, enhancing the downregulation of Natural Killer (NK) cell activators and death ligands, and evading killing by NK cells." (PMID 37296983, 2023). "In fact, the expression of the Wnt inhibitor Dickkopf-related protein 1 (DKK1) has been reported to induce cancer cells into quiescence." (PMID 36835173, 2023). "As discussed in more detail in Section 5 and Section 6, targeting osteocyte-derived factors regulating bone resorption (i.e., RANKL) or formation (i.e., sclerostin or DKK-1) also has an impact on the progression of cancers that grow in bone." (PMID 37174109, 2023). "We explored the function of cancer cell-specific DKK-1 in PCa growth, metastasis, and cancer–bone interactions using the osteoblastic canine PCa cell line, Probasco." (PMID 38067123, 2023). "Our data indicate that these studies would benefit from patient stratification depending on the DKK1 status of the cancer." (PMID 35924447, 2023). "The effect of DKK1 in progression of cancer both in in vitro and in vivo models is well established." (PMID 36661526, 2023). "According to research, lithium chloride usually encourages the spread of cancer cells, while Wnt signaling suppression via DKK1 reduces invasion in many cancers." (PMID 37635248, 2023). "Although the mechanism of DKK1 in regulating Wnt signaling is unclear, importantly, DKK1 overexpression has been observed in many types of cancer, and the inhibition of DKK1 suppresses tumorigenesis in several cancers." (PMID 37190019, 2023). "Secreted DKK1 can be specifically targeted with DKN‐01 a neutralizing antibody that has been shown to reduce cancer growth in models of both melanoma and prostate cancer in an NK cell‐dependent manner." (PMID 35924447, 2023).
cancer (continued). "Our data showed that overexpression of DKK1 in LGR4-silenced cancer cells successfully rescued the reduced OP recruitment." (PMID 34847079, 2022). "Though a significant portion of the article explores the effects of combination therapy in various cancer cell lines, serum DKK-1 concentrations in xenografted mice were reduced by 25% in treated mice compared to untreated." (PMID 36579200, 2022). "Given the role of cWnt in the stimulation of proliferation in many systems and cancers, a pro-tumorigenic role for Dkk-1 is surprising but quite feasible given the multiple roles for cWnt, the countless variants of Wnts and various non-canonical pathways." (PMID 35277659, 2022). "As expected, the protein level of DKK1 in the culture medium of dobutamine-treated BRCA1 knock-down cancer cells was elevated." (PMID 35517499, 2022). "DKK1 has emerged as an indispensable regulatory factor in multiple cancers and commonly existed as an inhibitor of the Wnt pathway." (PMID 36185284, 2022). "Survival analysis according to cancer stage was also performed, revealing that stage III was most associated with UC.145, DKK1, and PRKG1-AS1." (PMID 35625973, 2022). "Taken together, these data indicate that DKK-1 not only promotes cell proliferation and invasion in cancer cells but also activates the angiogenesis pathway in vascular endothelial cells." (PMID 35269944, 2022). "In particular, one of the aims of the study was to determine why the expression of DKK1, a potent inhibitor of the Wnt signaling pathway in many cancers, has been shown to have conflicting effects in GC." (PMID 35625973, 2022). "DKK1 increases the expression of SLC7A11 to protect metastasizing cancer cells from lipid peroxidation and ferroptosis." (PMID 35296660, 2022). "DKK1 plays a role in cancer proliferation, invasion, and growth via the modulation of Wnt signaling." (PMID 35121803, 2022). "In this study, we analyzed and correlated UC.145 expression with that of DKK1, an inhibitor of the canonical Wnt pathway involved in various cancers." (PMID 35625973, 2022). "Our data showed that knockdown of DKK1 in cancer cells successfully reduced the RSPO2- or RANKL-induced OP recruitment and osteoclast number and activity in tibiae and spines." (PMID 34847079, 2022). "The expression of DKK-1 was higher in isolated EpCAM+ cancer stem cells compared with that in EpCAM− cells." (PMID 35269944, 2022). "On the other hand, DKK1, CTSB, CTSD, BCLX, CSF1, and CAPG are associated with the metastatic potential of cancer." (PMID 35745691, 2022). "Consistent with this, knocking down DKK1 inhibited the ability of LGR4-overexpressing cancer cells to attract OPs." (PMID 34847079, 2022). "DKK1 is a secretory Wnt antagonist, and abnormal expression of DKK1 has become recognized as an important regulator of many human cancers." (PMID 35907982, 2022). "This is particularly important in cancer, where DKK1 has been evaluated as a prognostic biomarker with ambiguous results." (PMID 36539532, 2022). "DKK1 maintains the elevated inflammatory tone of cancer cells and is required for mounting cytokine responses following ligation of toll-like and cytokine receptors." (PMID 36539532, 2022). "Many studies have shown that DKK1 plays various roles in Wnt signaling during several cancers, which correlates with the overall survival of OSCC patients." (PMID 35493294, 2022). "DKK1 is a Wnt signaling pathway suppressor, and its dysregulation has recently been identified as a possible biomarker for cancer development and prognosis in a variety of malignancies." (PMID 35983409, 2022). "It has been reported that enhanced serum level of DKK1 is correlated with a poor prognosis in cancer patients." (PMID 35517499, 2022). "In the premetastatic niche in vivo model, overexpression of DKK1 in human SCP46 cancer cells restored the serum level of human DKK1 protein inhibited by LGR4 knockdown and reversed the effects of LGR4 silencing on OP number and osteoclast number and activity." (PMID 34847079, 2022).
cancer (continued). "Collectively, these data suggest that DKK1 promotes inflammatory cytokine expression in cancer cells in a cell-autonomous fashion." (PMID 36539532, 2022). "Dickkopf Wnt signaling pathway inhibitor 1 (DKK1) inhibits Wnt/β-catenin signaling and has been reported in various human diseases, particularly malignant tumors." (PMID 35625973, 2022). "In oral squamous cell carcinoma (OSCC) cells, miR-1-3p suppressed the progression of OSCC by attenuating DKK1 expression and thereby triggering apoptosis, which implied its potential for cancer treatment." (PMID 35355709, 2022). "ET1 secreted by cancer cells in the bone microenvironment, known as a major mediator of bone deposition, was found to downregulate the expression of DKK1 and to upregulate the expression of Wnt5a." (PMID 36497192, 2022). "Taken together, these findings suggest that DKK1 expression correlates with an inflammatory phenotype in cancer." (PMID 36539532, 2022). "Dickkopf‐1 (Dkk1) is an inhibitor of Wnt signaling involved in cancer cell proliferation, apoptosis, and migration and angiogenesis." (PMID 33639034, 2021). "Our analysis of DKK1 gene profile using data from TCGA also proves the high expression of DKK1 in 14 types of cancers." (PMID 34093545, 2021). "There is in vitro evidence suggesting the induction of Dkk-1 gene transcription by 1,25OH2D in cancer cells and in osteoblasts." (PMID 34371803, 2021). "DKK1, as a negative regulator of canonical Wnt signaling, has been an emerging topic of experimental as well as clinical research for cancer patients." (PMID 34638464, 2021). "As mentioned, DKK1 was highly expressed in a great variety of cancers and also involved in cancer progression." (PMID 34093545, 2021). "While the functional role of DKK1 in cancer progression has been evaluated frequently in the past, the impact on the pathogenesis of EAC remains poorly understood." (PMID 34638464, 2021). "Based on these findings, it is necessary to evaluate the role of DKK1 in the cancer immune microenvironment." (PMID 34899842, 2021). "Dysregulation of DKK1 has recently emerged as a potential biomarker of cancer progression and prognosis for several types of malignancies." (PMID 34093545, 2021). "In this study, multiple bioinformatic analyses were conducted to evaluate therapeutic value of DKK1 in human cancers." (PMID 34899842, 2021). "At present, DKK1 has been developed as a serological marker for the diagnosis and prognosis evaluation of several cancers, and also a new target for cancer treatment." (PMID 34803487, 2021). "In this study, expression difference analyses of DKK1 were performed between cancer tissues and adjacent normal tissues." (PMID 34899842, 2021). "Although serum DKK-1 has been reported as a useful biomarker in several cancers, its clinical implications are controversial." (PMID 33921232, 2021). "Among all eligible candidate genes, DKK1 is a WNT signaling regulator that plays important role in multiple cancer types." (PMID 34697293, 2021). "DKK-1 is typically considered as an antagonist for the Wnt signaling pathway, which regulates the differentiation, proliferation, and migration of cancer cells." (PMID 34123800, 2021). "Numerous preclinical studies have demonstrated the cancer-promoting effects of DKK1 in both in vitro cell models and in vivo animal models." (PMID 34093545, 2021). "Our prognostic analysis showed that in most cancers (ACC, HNSC, LAML, LUAD, MESO, PAAD, and STAD), the upregulated expression of DKK1 was associated with poor prognosis." (PMID 34899842, 2021). "For example, the activity of the anti-DKK1 antibody DKN-01 was dependent on a functional immune system in the murine cancer model." (PMID 34093545, 2021). "Emerging experimental evidence indicates that DKK1 has been involved in T cell differentiation and induction of cancer evasion of immune surveillance by accumulating MDSCs." (PMID 34093545, 2021).
cancer (continued). "From the results, the expression level of DKK1 was significantly positively correlated with infiltrating levels of MDSCs in 20 types of cancers, suggesting DKK1 is involved in MDSCs modulation in a variety of cancers." (PMID 34093545, 2021). "In this study, we evaluated the pan-cancer expression of DKK1 using The Cancer Genome Atlas (TCGA) dataset." (PMID 34899842, 2021). "DKK1 overexpression enhanced proliferation, invasion, migration and vascular invasion of cancer cells." (PMID 34093545, 2021). "By inhibiting β-catenin to prevent clearance by natural killer (NK) cells, DKK1 helps to sustain the stem cell-like properties of cancer cells." (PMID 34899842, 2021). "As an important regulator of Wnt signaling, DKK1 is involved in cancer cell proliferation, apoptosis, and migration and in angiogenesis." (PMID 33639034, 2021). "Investigating the role of DKK1 in neovascularization will benefit both for the cancer and CVD treatment at the same time." (PMID 34803487, 2021). "In view of this, the therapeutics approach against DKK1 should be examined regarding the dichotomous function of DKK1 in cancer metastasis organotropism." (PMID 34093545, 2021). "Dickkopf1 (DKK1) plays many roles in both tumors and AS and has emerged as a potential biomarker of cancer progression and prognosis." (PMID 34803487, 2021). "More importantly, there is growing evidence that DKK1 plays an essential role in cancer progression." (PMID 34093545, 2021). "Currently, DKK1 expression is abnormal in many kinds of tumors, and there is a significant correlation between DKK1 expression and cancer prognosis." (PMID 33639034, 2021). "We found that all three genes (SERPINE1, COL1A1, and DKK1) had been reported to be closely related to cancer progression." (PMID 33969120, 2021). "Despite the fact that DKK-1 has been studied in several cancers, little is known about its function in pediatric tumors." (PMID 34884726, 2021). "A FOXM1 binding site was identified in the 5ʹ-untranslated region of the DKK1 gene, and its depletion decreased DKK1 expression and cancer cell proliferation." (PMID 34117362, 2021). "In recent clinical studies, dysregulation of the DKK1 was highlighted in various cancers including angiogenesis, metastasis, and other advanced invasion, and this was usually associated with poor prognosis." (PMID 34093545, 2021). "Dickkopf1 (DKK1) is overexpressed in various cancers and promotes cancer cell proliferation by binding to cytoskeleton-associated protein 4 (CKAP4)." (PMID 34117362, 2021). "Clinical studies in a range of cancers have detected elevated levels of the Wnt antagonist Dickkopf-1 (DKK1) in the serum or tumors of patients, and this was frequently associated with a poor prognosis." (PMID 34093545, 2021). "We inquired on the mRNA expression of DKK1 in different types of cancers and its correlation with the abundance of immune infiltrates." (PMID 34093545, 2021). "Reduced expression of DKK1 induced inhibition of cancer cell proliferation, colony formation, migration and invasion." (PMID 34093545, 2021). "DKK1 mRNA expression in cancer tissues from the TCGA database was inconsistent with that in GTEx and TCGA normal tissues." (PMID 34899842, 2021). "It turned out that DKK1 was strongly correlated with the immune cell infiltration in many types of cancer (|r| > 0.4, p < 0.05)." (PMID 34899842, 2021). "The Wilcoxon rank test was performed to evaluate the expression difference of DKK1 between cancer tissues and normal tissues." (PMID 34899842, 2021). "Further characterization indicates that CKAP4 interacted with phosphatidylinositol 3-kinase (PI3K) and DKK1, leads to the activation of Akt signaling and increases the proliferation of the cancer cells." (PMID 34093545, 2021). "Annexin A3-like DKK1, plays an important role in cancer cell formation and proliferation, as well as in their apoptosis and signaling transmission." (PMID 35011815, 2021).